NLRP3 (NLR family pyrin domain containing 3)
Diseases named in the same sentence as NLRP3 in open-access papers (continued):
Sharing a sentence is not in itself a finding about the gene and the disease.
gout (continued). "In mice with monosodium urate (MSU)-induced gout, Treg-of-B cells migrate into draining lymph nodes to mitigate arthritis through repressing NLR family pyrin domain containing 3(NLRP3)-related inflammation triggered by macrophages." (PMID 36211467, 2022). "In summary, the study indicated that Cyn suppressed gouty arthritis induced by monosodium urate crystals by regulating NF-κB, JNK pathways and NLRP3 inflammasomes." (PMID 35546047, 2022). "The samples from both protocols demonstrate PIP pharmacodynamics in the inhibition of the NLRP3 inflammasome cascade that suppresses leukocyte migration and degradation in the exudate during MSU-induced gout inflammation." (PMID 35400961, 2022). "In the MSU-induced acute gouty arthritis model, the P2Y14 receptor (P2Y14R) activates the NLRP3 inflammasome, promotes caspase-1 expression, and increases pyroptosis in macrophages." (PMID 35411030, 2022). "However, whether corilagin targets NLRP3 to treat gouty arthritis is unknown." (PMID 36299604, 2022). "Here, we aimed to investigate the therapeutic implications of targeting P2X7R in gout by designing a P2X7R allosteric inhibitor and validating the inhibitory function on NLRP3 inflammasome activation." (PMID 36052144, 2022). "TRIM65-dificiency enhances disease severity in multiple mouse models of NLRP3-dependent acute inflammatory diseases: LPS-induced systemic inflammation and MSU-induced peritonitis and gouty arthritis." (PMID 34512673, 2021). "Mitochondrial DNA copy number variation was consistent with emerging research showing that mitochondria are important for the colocalization of the NLRP3 and ASC inflammasome subunits, a process essential for the generation of interleukin-1β in gout." (PMID 33926105, 2021). "IL-1β is an important inflammatory mediator of gouty arthritis, which is mainly produced through the TLR4-NF-κB and NLRP3 inflammasome signaling pathways." (PMID 33935726, 2021). "Therefore, the NLRP3 inflammasome could be a potential target for gout therapy." (PMID 33670601, 2021). "The results of cell experiments were highly consistent with the results of the animal experiments, further suggesting that the active flavonoids can attenuate gouty arthritis by regulating the TLR4/MyD88/NF-κB pathway and NLRP3 levels." (PMID 34803702, 2021). "This study examined the effects of temperature on inflammasome activation in murine macrophages and found that a lower temperature increased the activation of NLRP3 inflammasome in response to MSU crystals, resulting in gout." (PMID 34440688, 2021). "Activation of NLRP3 inflammasome promotes MSU crystal-induced inflammation in macrophages, while its inactivation averts gout by reducing the production of IL-1β." (PMID 33505510, 2021). "Thus, we conclude that wedelolactone partially suppresses the production of MSU‐elevated IL‐1β and caspase‐1 (p20) in vivo, thereby limiting NLRP3 inflammasome activation and neutrophil influx, suggesting that wedelolactone may be a potential candidate in the treatment of gouty arthritis." (PMID 32656909, 2020). "Because NLRP3 inflammasome is a key component in the response to MSU crystals, strategies that prevent their activation or affect their activity can relieve gout inflammation." (PMID 33488933, 2020). "Meanwhile, western blot and immunofluorescence data demonstrated that the enhanced cAMP level attenuated the MSU-induced activation of the NLRP3 signaling pathway, suggesting the crucial role of cAMP in the regulation of P2Y14R-mediated gouty arthritis." (PMID 32457291, 2020). "Procyanidins attenuated gout pain and suppressed ankle swelling and inhibited MSU-induced activation of the NLRP3 inflammasome and increase of IL-1β." (PMID 32973552, 2020). "In addition, clinical trials have observed that the blockade of NLRP3 downstream signaling with IL-1 inhibitors, including rilonacept, canakinumab, and anakinra counteracted joint inflammation and attenuated the disease severity in patients with acute and chronic gout." (PMID 31200447, 2019).
gout (continued). "The NLRP3 inflammasome, a protein complex, has been reported playing an important role in the MSU-induced gouty arthritis." (PMID 31885675, 2019). "As illustrated in some research studies, NOD-like receptor protein-3 inflammasome (NLRP3) and toll-like receptor-4 (TLR4) plays an important role during gouty arthritis." (PMID 32082152, 2019). "NLRP3 inflammasome, a member of nucleotide-binding oligomerization domain- (NOD-) like receptor (NLR) family, plays critical roles in gouty arthritis and many pathological inflammatory conditions." (PMID 31885675, 2019). "Considering the high safety of TR in clinic, our study provides a potentially new and practical pharmacological approach for treating NLRP3‐driven diseases, including CAPS, type 2 diabetes, and gout." (PMID 29531021, 2018). "On the basis of evidence described in this study and the favorable phase I safety profile, oral OLT1177 has advanced into three phase II development programs, including gout, establishing the translational value of OLT1177 as a safe oral NLRP3 inhibitor." (PMID 30075804, 2018). "An increased risk of incident MI in people with gout raises a question regarding the role of chronic inflammation and IL-1β pathways (via NLRP3 inflammasome activation) and CRP, hallmarks of gout, in the pathogenesis of MI." (PMID 29859125, 2018). "In corroboration, the flavonoid quercetin that inhibits NLRP3 inflammasome and ASC speck formation reduces pain and inflammation in experimental gout." (PMID 30319413, 2018). "It suggested that genes which regulate inflammation and immunology such as NLRP3, except for genes which regulate urate homeostasis such as SLC2A9, were involved in the pathogenesis of gout." (PMID 29214547, 2018). "Third, in the murine acute gouty arthritis model, qPCR-array and western blot analysis indicated that IL-1R8, Smad3 and S​OCS3 were highly expressed, whereas NLRP3 was suppressed in the rhIL-37 intervention groups." (PMID 27863506, 2016). "IL-1β-dependent inflammation, occurring in a number of diseases in addition to gout, depends on the MSU-induced formation of a macromolecular nucleotide-binding domain-like receptor protein 3 (NLRP3) inflammasome complex." (PMID 25897296, 2015). "The NLRP3 inflammasome seems to be able to sense non-microbial molecules, or, in other words, it can be activated in the context of “sterile inflammation” (Chen and Nuñez, 2010), and it has been implicated in various sterile inflammatory diseases, including gout, asbestosis and silicosis." (PMID 23060876, 2012). "Epigenetic modifications and post-translational modifications (PTMs) may contribute to the progression from HUA to gout by modulating the function of UA transporters such as ABCG2 and GLUT9 and involving the NLRP3/IL-β inflammatory axis." (PMID 42293766, 2026). "Well-known for preserving cartilage integrity, recombinant human proteoglycan-4 exerts its anti-gout properties by restraining phagocytosis of MSU crystals, NF-κB nuclear translocation, and NLRP3 inflammasome activation in macrophages due to its interaction with CD44 (mainly) and TLR2/4 (partially)." (PMID 39935474, 2025). "Conversely, in gout, reduced bile acid levels lead to diminished TGR5 activity, which in turn results in reduced GLP-1 secretion, and weakened inhibition of both the NF-κB pathway and NLRP3 inflammasome." (PMID 41255527, 2025). "As such, blockade of the NLRP3 inflammasome with canakinumab reduced incident gout without altering SU levels." (PMID 39862678, 2025). "Gouty arthritis (GA), a condition characterized by monosodium urate (MSU) crystal deposition and NLRP3 inflammasome-driven inflammation, is a result of a complex interplay between hyperuricemia and immune dysregulation, which leads to systemic complications and joint damage." (PMID 41181107, 2025). "This study investigated whether combining disulfiram (DSF), a known NLRP3 inflammasome inhibitor, with ALP enhances therapeutic outcomes in a rat model of gout." (PMID 40430581, 2025).
gout (continued). "The NLRP3 inflammasome plays significant roles in aging and metabolism-related disorders, as it can be activated by MSU crystals and CPPD crystals, which are the etiological agents of the acute inflammatory conditions gout and pseudogout, respectively." (PMID 40508226, 2025). "CIPs contribute to the inflammatory process in gout, primarily through the activation of Toll-like receptors (TLRs) and the NOD-like receptor pyrin domain containing 3 (NLRP3) inflammasome by MSU crystals, which leads to the release of pro-inflammatory mediators." (PMID 40388724, 2025). "While targeting interleukins is pathway-specific, colchicine outside its use in gout has recently been introduced as an immunomodulatory drug in IHD due to its properties as a non-selective NLRP3 inhibitor." (PMID 39969632, 2025). "Its specific anti-inflammatory action has been validated in murine models of gouty arthritis and peritonitis, demonstrating selective targeting of NLRP3 without affecting other inflammasomes." (PMID 40520933, 2025). "Although no significant change in the expression of NLRP3 after supplementation with butyrate was observed in both the gout and peritonitis models, supplementation with butyrate effectively suppressed the production of caspase-1 and IL-1β." (PMID 39907694, 2025). "The variability in the types of crystals found in RP may favor distinct inflammatory responses in the papillae potentially involving the NLRP3 inflammasome and macrophage-mediated inflammation, similar to MSU crystals in gout." (PMID 40944726, 2025). "Notably, among approved anti-gout drugs, colchicine completely abrogated NCOA6 expression and speck formation in activated macrophages, suggesting that colchicine inhibits NLRP3 inflammasome activity by targeting NCOA6." (PMID 38195836, 2024). "Recently, HMG-CoA reductase inhibitors including atorvastatin, simvastatin, and mevastatin inhibited the activation of the MSU-induced NLRP3 inflammasome by the up-regulation of the peroxisome proliferator-activated receptor-γ (PPAR-γ), resulting in anti-inflammatory therapeutic action in gout." (PMID 39065733, 2024). "In the present work, an NLRP3 inflammasome activation experiment system was used in mouse bone marrow macrophages combined with in vivo mouse models to investigate the effect of ER on HUA and gout." (PMID 38708084, 2024). "NLRP3 inflammasome is involved in the pathogenesis of HUA and gout as a sensor of metabolic stress, and targeted inhibition of NLRP3 inflammasome may be a key strategy for the prevention and treatment of HUA and gout." (PMID 38708084, 2024). "Here, our results showed that pharmacological blockage of NLRP3 inflammasome remarkably attenuated TRPV1 overexpression in sensory neurons of gout mice, indicating NLRP3 inflammasome contributes to TRPV1 overexpression in gout condition." (PMID 37464384, 2023). "In a mouse model of gouty arthritis involving MSU injection into the ankle joint, this induced ankle oedema, mechanical allodynia, neutrophil infiltration, oxidative stress, NLRP3 inflammasome activation and increased production of the pro-inflammatory cytokines, IL-1β and TNFα." (PMID 37106238, 2023). "Finally, statins play a potent anti-inflammatory role in NLRP3 inflammasome activation by augmenting PPAR-γ production and thereby strengthening its inhibition of ROS generation in gout." (PMID 37111279, 2023). "In an attempt to develop novel inhibitors of the NLRP3 inflammasome acting on NEK7, we identified an NLRP3 inhibitor blocking NEK7 binding to NLRP3 and investigated its effect on an MSU-induced gout animal model, which mimics human gout arthritis pathogenically linked to the inflammasome." (PMID 38371945, 2023). "In the acute gouty arthritis model of rats, WSP treatment inhibited significant foot swelling, attenuated pathological lesions, and downregulated the related protein expression of NLRP3 inflammasome signaling in synovial tissue of the ankle." (PMID 37637422, 2023).
gout (continued). "Furthermore, a recent discovery of the NLRP3 assemblage in T cells, which is known to be activated by MSU crystals in innate immune cells and to drive inflammatory flares in gout, suggests that adaptive immune cells can also be involved in gout pathology." (PMID 37714974, 2023). "In the pathological process of gout, the increased expression of XOD can promote the production of uric acid, disrupt the balance of oxidative stress, generate a large amount of ROS, activate the NLRP3 inflammasome, and release IL-1β." (PMID 36569836, 2022). "Although much progress has been made in elucidating the biological pathways that mediate gout attacks, the precise mechanism by which endocytosed MSU crystals activate the NLRP3 inflammasome remains unclear." (PMID 35370689, 2022). "Therefore, in the present study, the underlying protective role and mechanism of ELB involved in TLR4/NF-κB, NLRP3, and JAK2/STAT3 inflammatory signaling pathways were investigated in chronic alcoholic liver injury combined with gouty arthritis." (PMID 36176434, 2022). "In gouty arthritis, MSU crystal acts as a ligand to bind and activate NLRP3 inflammasome." (PMID 36034424, 2022). "Previous studies revealed that the NOD-like receptor signaling pathway, especially the NLRP3 inflammasome, plays an important role in the pathogenesis of AGA; therefore, we mainly investigated the effect of PEL on the NLRP3/ASC/caspase-1 pathway in gout rats." (PMID 35449811, 2022). "Therefore, PIP is capable of disrupting the NLRP3 inflammasome and has the potential to inhibit CRP production during the acute phase of gout inflammation." (PMID 35400961, 2022). "Because of its central role in regulating the NLRP3 inflammasome, the MAPK/NF-κB axis may represent a promising therapeutic target for gout management strategies." (PMID 35400961, 2022). "In conclusion, the current study indicates that ELB exhibits a protective effect in rats with chronic alcoholic liver injury and gouty arthritis, possibly mediated by inhibiting TLR4/MyD88/NF-κB, NLRP3, and JAK2-STAT3 signaling pathways in both the hepatic and synovial tissues." (PMID 36176434, 2022). "Although pathologically it has been firmly established that the activation of the NLRP3 inflammasome and IL-1β is important in the pathogenesis of gout, the interactive mechanism between MSU and cells has not been clearly elucidated." (PMID 35370689, 2022). "The immune response during the development of hyperuricemia to gouty arthritis may be due to the increased expression of XOD, which promotes the production of uric acid, activates the release of ROS, and then activates the NLRP3 inflammasome and release IL-1β." (PMID 36569836, 2022). "Previous studies have suggested that the activation of NLRP3 inflammasome induced by MSU crystal can result in pyroptosis and secretion of interleukin (IL)-1β, exacerbating inflammatory damage and progression of gout." (PMID 36569930, 2022). "Disulfiram inhibits NLRP3 activation by inhibiting the release of lysosomal histone B into the cytoplasmic lysate and inhibiting mitochondrial ROS production and has significant efficacy against MSU-induced gout inflammation." (PMID 35464445, 2022). "Eucalyptol inhibited inflammatory cell infiltration, upregulation of TRPV1 expression, activation of the NLRP3 inflammasome, and production of pro-inflammatory cytokines induced by MSU injection in mouse ankle joints to suppress gout and joint inflammation primarily through antioxidant mechanisms." (PMID 35464445, 2022). "For example, soluble decoy receptor 3 (DcR3) promotes the differentiation of anti-inflammatory M2 macrophages and inhibits NLRP3 activation by reducing MSU-induced mitochondrial dysfunction and lysosomal rupture to decrease ROS production and cathepsin levels and to improve gout." (PMID 35464445, 2022). "Nonetheless, the effects of cardamonin on MSU-stimulated gouty arthritis via the NLRP3 inflammasome signal pathway have not been extensively investigated." (PMID 34577821, 2021).
gout (continued). "Thus, in acute gouty arthritis, the activation of the P2Y14 receptor can exert a pro-inflammatory effect through the cAMP/NLRP3 signaling pathway." (PMID 34925366, 2021). "In an acute gout mouse model, oral administration of sulforaphane (SFN) attenuated MSU crystal-induced swelling and neutrophil recruitment thus indicating inhibition of NLRP3 inflammatory activation in the foot tissue." (PMID 33534121, 2021). "Therefore, oral administration of loganin prevents the inflammatory symptoms of gouty arthritis induced by MSU crystals deposition, mediated by the suppression of NLRP3 inflammasome activation." (PMID 33670601, 2021). "In the present study, the effects of the active flavonoids were evaluated in rats or Raw264.7 cells with gouty arthritis induced by monosodium urate (MSU) crystal, followed by the detection of TLR4, MyD88, pNF-κB, and NLR family pyrin domain-containing 3 (NLRP3) expression." (PMID 34803702, 2021). "In gout and acute CPP crystal arthritis, the crystals taken up by macrophages first enhance pro-IL-1β expression during the priming phase and then promote the assembly and activation of the NLRP3 inflammasome." (PMID 33926523, 2021). "Our results show that MSU crystal-induced NETs are engulfed by synovial fluid macrophages in patients with gouty arthritis, independent of the activation of the NLRP3 inflammasome." (PMID 33741037, 2021). "In conclusion, the present study demonstrated that three active flavonoids (luteolin, luteoloside, and apigenin) from Lagotis brachystachya attenuate MSU crystal-induced gouty arthritis via inhibiting TLR4/MyD88/NF-κB and NLRP3 expression in the aspect of animal experiment and cell experiment." (PMID 34803702, 2021). "It is reported that gout is closely related to inflammatory response and regulates the activation of typical inflammatory pathways such as toll-like receptor (TLR) 4-NFkappaB-IL-1β signaling, and NLRP3-IL-1β signaling pathway." (PMID 34874227, 2021). "We next investigate whether wedelolactone could inhibit the NLRP3 inflammasome activation in MSU‐induced peritonitis and gouty arthritis in C57BL/6J mice." (PMID 32656909, 2020). "Monocytes from gout patients were more responsive to priming, but not activation, of the NLRP3 inflammasome." (PMID 30761138, 2019). "The inhibition of NLRP3 by QZTB, evidenced by the decreased mRNA and protein expressions of NLRP3 in the ankle joint, and the lower production of serum IL-1β and TNF-α level, further indicates the efficacy of QZTB on gouty arthritis in clinic." (PMID 31885675, 2019). "The pathogenesis of gouty arthritis has also been correlated with IL-1β via TNF-α, and NLRP3 inflammasome activation in macrophages and chemokines and an IL-1β antibody has been shown to provide superior inflammation prophylaxis than colchicine in patients with gout." (PMID 30854012, 2019). "Oral treatment of TR improved the symptoms of metabolic disorders or gouty arthritis in wild‐type mice, but not in Nlrp3−/− mice, suggesting the beneficial effects of TR depend on its suppressive activity for NLRP3 inflammasome." (PMID 29531021, 2018). "The present experiment is a single center study, and lack of functional experiments to confirm the role of NLRP3 SNPs in gout." (PMID 29214547, 2018). "Although the involvement of TLRs, NLRP3 inflammasome, and IL-1β in the MSU-induced inflammatory reaction is well-known, there are no miRNAs discovered, thus far, directly targeting TLRs, IL-1β, chemokines, and NLRP3 in gout." (PMID 27845712, 2016). "Based on the anti-inflammatory action of berberine, the study is to investigate the effects of berberine on NLRP3 and IL-1β in THP-1 cells with MSU crystals-induced inflammation on the basis of our previous research and to provide evidence for its application in gouty arthritis." (PMID 27689075, 2016).